PFN4 (profilin family member 4)
Description:
Involved in male fertility. Required for manchette development and acrosome biogenesis during spermiogenesis (By similarity). Binds in vitro to phospholipids, including phosphatidylinositol 3-phosphate (PtdIns(3)P), phosphatidylinositol 4,5-bisphosphate (PtdIns(4,5)P2), phosphatidylinositol 4-phosphate (PtdIns(4)P) and phosphatidic acid (PA). Contrary to other profilin family members, does not bind to actin in vitro.
Tractability: No criterion of Open Targets' tractability assessment is met for any kind of drug.
Gene: Protein-coding gene on chromosome 2 (24,114,637 to 24,123,734, reverse strand). Ensembl gene ENSG00000176732.
Subcellular location: Cytoplasm
Gene Ontology:
Molecular function: actin monomer binding; actin binding
Biological process: acrosome assembly; flagellated sperm motility; manchette assembly; sperm flagellum assembly; spermatogenesis
Cellular component: cytoplasm; cell cortex
Genetic constraint (gnomAD): Loss-of-function variants: 7 observed, 9.95 expected, observed/expected ratio (o/e) 0.7, 90% interval 0.4 to 1.32. That is too few expected variants to judge how well the gene tolerates losing a copy. Missense variants: 103 observed, 121.34 expected, observed/expected ratio (o/e) 0.85, 90% interval 0.72 to 1. Synonymous variants: 45 observed, 47.66 expected, observed/expected ratio (o/e) 0.94, 90% interval 0.74 to 1.21.
Homologues: Orthologues: chimpanzee PFN4 (100% identical), macaque PFN4 (95% identical), pig PFN4 (71% identical), mouse Pfn4 (70% identical), rat Pfn4 (68% identical), guinea pig PFN4 (67% identical), tropical clawed frog pfn4 (41% identical), zebrafish pfn4 (40% identical), Drosophila melanogaster chic (26% identical), Caenorhabditis elegans pfn-3 (22% identical).
Diseases named in the same sentence as PFN4 in open-access papers:
PFN4 is named in the same sentence as 3 diseases in open-access papers, as found by Europe PMC text mining. Sharing a sentence is not in itself a finding about the gene and the disease. The quoted sentences say what the papers report.
male infertility (2 papers, 2009 to 2022). The inability of the male to effect fertilization of an ovum after a specified period of unprotected intercourse. "This indicates that the acrosome defects in Pfn4−/− sperm contribute to male infertility in PFN4-deficient mice." (PMID 35950913, 2022). "PFN4-deficient males show disturbed spermatogenesis, resulting in male infertility." (PMID 35950913, 2022). "An F-actin independent role of PFN4 may suggest novel functions related to the process of spermatid head shaping, and may have significant clinical implications in understanding idiopathic causes of male infertility associated with abnormal sperm head shaping." (PMID 19419568, 2009). "Thus, impaired acrosome biogenesis seems to be responsible, at least in part, for the Pfn4−/− male infertility." (PMID 35950913, 2022). "Here, we have established and analyzed mouse lines deficient in PFN4 and demonstrate that lack of PFN4 leads to male infertility." (PMID 35950913, 2022).
infertile (1 paper, 2022). "In vitro fertilization demonstrated that PFN4-deficient sperm is capable of fertilizing zona-free oocytes, suggesting a potential treatment for PFN4-related human infertility." (PMID 35950913, 2022).
neurodegenerative disease (1 paper, 2022). A disorder of the central nervous system characterized by gradual and progressive loss of neural tissue and neurologic function. "Finally, several proteins that are associated with neurodegenerative diseases were upregulated either during isolation (Pfn4, C1qb, Bag5 and Sv2c) or following regrouping (oxidative phosphorylation-associated genes such as Ndufc2)." (PMID 34650208, 2022).